MIR616 (microRNA 616)
Synonyms: hsa-mir-616; MIRN616
Gene: MicroRNA gene on chromosome 12 (57,519,163 to 57,519,259, reverse strand). Ensembl gene ENSG00000208028.
Gene Ontology:
Biological process: miRNA-mediated post-transcriptional gene silencing